ARL16 (ARF like GTPase 16)
Description:
Required for the trafficking of ciliary proteins IFT140 and INPP5E from the Golgi to the cilia, thus playing a role in ciliogenesis (By similarity). Suppresses the RNA sensing activity of RIGI in a GTP-dependent manner.
Gene: Protein-coding gene on chromosome 17 (81,681,165 to 81,683,797, reverse strand). Ensembl gene ENSG00000214087.
Subcellular location: Cytoplasm; Cytoplasm, cytoskeleton, cilium axoneme; Mitochondrion; Cytoplasm, cytoskeleton, cilium basal body; Photoreceptor inner segment
Subcellular location (Human Protein Atlas): Basal body; Primary cilium
Genetic constraint (gnomAD): Loss-of-function variants: 27 observed, 17.25 expected, observed/expected ratio (o/e) 1.57, 90% interval 1.14 to 1.93. The synonymous counts are far from expectation, so gnomAD's model fits this gene poorly and the ratio says little. Missense variants: 248 observed, 222.17 expected, observed/expected ratio (o/e) 1.12, 90% interval 1.01 to 1.24. Synonymous variants: 122 observed, 93.4 expected, observed/expected ratio (o/e) 1.31, 90% interval 1.13 to 1.52.
Homologues: Orthologues: chimpanzee ARL16 (100% identical), macaque ARL16 (96% identical), mouse Arl16 (85% identical), rat Arl16 (84% identical), guinea pig ARL16 (81% identical), pig ARL16 (53% identical), dog ARL16 (53% identical). Paralogues in human: ARF1 (30% identical), ARL1 (30% identical), TRIM23 (30% identical), ARF3 (29% identical), ARF4 (29% identical), ARF5 (28% identical), ARF6 (28% identical), ARL14 (28% identical), ARL3 (28% identical), ARL5B (28% identical), ARL2 (27% identical), ARL5A (27% identical), and 18 more.
Diseases named in the same sentence as ARL16 in open-access papers:
ARL16 is named in the same sentence as 7 diseases in open-access papers, as found by Europe PMC text mining. Sharing a sentence is not in itself a finding about the gene and the disease. The quoted sentences say what the papers report.
acute myeloid leukemia (1 paper, 2024). Acute myeloid leukemia (AML) is a group of neoplasms arising from precursor cells committed to the myeloid cell-line differentiation. "Interestingly, MYTHO has been reported to be fused in frame with ABCC6 and ARL16 genes in acute myeloid leukemia and lung squamous cell carcinoma, but the pathogenetic role of the fused transcripts has not yet been explored." (PMID 38869949, 2024).
endometrial cancer (1 paper, 2022). Primary or metastatic malignant neoplasm involving the endometrium (mucous membrane that lines the endometrial cavity). "In the case of the ADP-ribosylation factor (ARF)/ARF-like protein (ARL) family, it was observed that a high expression of ARL4D, ARL1, ARF1, and SAR1B in endometrial cancer is associated with better prognosis, while a high expression of ARL4C, ARL2, ARL10, ARL16, and ARL14 promotes worse survival." (PMID 35163161, 2022).
Strabismus (1 paper, 2019). A misalignment of the eyes so that the visual axes deviate from bifoveal fixation. "These variants were associated with reduced TSPAN10 gene expression in brain tissues, although such eQTL effects were also observed for the adjacent genes PDE6G and ARL16, suggesting that the risk of strabismus could be mediated through any one or more of these genes." (PMID 31073882, 2019). "Thus, in summary, there was strong evidence that the causal variant underlying the association with strabismus acts as a cis-eQTL for TSPAN10 in neural tissue, and for PDE6G and ARL16 in certain other tissues." (PMID 31073882, 2019).
ARL16 also shares sentences with these, for which no sentence is quoted: cancer (3 papers); lung squamous cell carcinoma (1); prostate carcinoma (1); tumor (1).